NFS1 (NFS1 cysteine desulfurase)
Diseases named in the same sentence as NFS1 in open-access papers (continued):
Sharing a sentence is not in itself a finding about the gene and the disease.
cancer (42 papers, 2020 to 2026). A tumor composed of atypical neoplastic, often pleomorphic cells that invade other tissues. "Previous studies demonstrated that inhibition of Fe–S cluster synthesis by NFS1 depletion predisposes cancer cells to ferroptosis." (PMID 37059186, 2023). "Elevated oxygen concentration is more likely to damage ISC in cancer cells that have lower NFS1 expression, causing ferroptotic cell death." (PMID 36282248, 2022). "The knockdown of NFS1 cysteine desulfurase (the biosynthetic enzyme of the Fe-S cluster) makes cancer cells susceptible to ferroptosis." (PMID 33117818, 2020). "In addition to AIFM2 and NFS1, the remaining seven genes in the signature were also associated with cancer in both basic and clinical research fields." (PMID 34778244, 2021). "The development of potent and highly selective inhibitors targeting NFS1 is considered a promising therapeutic strategy for cancer treatment." (PMID 40141425, 2025). "NFS1 overexpression has been observed in a variety of cancers, and thus it has been considered a promising anti-tumor therapeutic target." (PMID 40141425, 2025). "NFS1 is a potential diagnostic and prognostic biomarker linked to ferroptosis and the TME, and provides a novel target for cancer treatment and immunotherapy." (PMID 40822970, 2025). "Cancer cells are highly dependent on elevated levels of the iron–sulfur cluster biosynthetic enzyme cysteine desulfurase (NFS1)." (PMID 40837737, 2025). "The review shows that NFS1 plays an important role in cellular fate regulation, which has significant clinical application potential in the treatment of cancer and interventions for neurological and cardiovascular diseases." (PMID 41594574, 2025). "In conclusion, our findings establish d-Cys as a potent NFS1 inhibitor with therapeutic potential for cancer treatment." (PMID 40797101, 2025). "Compound 53 can be utilized to investigate the biological roles of NFS1 and can serve as a lead compound for developing treatments for NFS1-related cancers." (PMID 40141425, 2025). "NFS1 has emerged as an important protein in different cancers and hence represents a promising target for therapeutic intervention." (PMID 40822970, 2025). "The direct mechanisms by which NFS1 influences cancer development and prognosis by controlling ferroptosis and TME need to be further studied using more fundamental studies with additional clinical samples." (PMID 40822970, 2025). "Targeting NFS1 to induce ferroptosis has been under investigation as a potential therapeutic strategy in several types of cancers." (PMID 40822970, 2025). "Recent studies have revealed the involvement of human NFS1 in the pathogenesis of various malignancies, highlighting its potential as a target for cancer therapy." (PMID 40141425, 2025). "One possible mechanism for this is that the higher expression level and enzyme activity of NFS1 are required in A549 cancer cells, as evidenced by Western blot analysis." (PMID 40141425, 2025). "Knockdown of NFS1 greatly decreased invasion, migration, and proliferation of the GC cell line according to in vitro experiments, which is consistent with previous results in other cancer types and indicates the role of NFS1 in carcinogenesis." (PMID 40822970, 2025). "GSEA based on NFS1 expression is related to the cell cycle, cancer, stroma, inflammatory responses, and ferroptosis metabolic pathways." (PMID 40822970, 2025). "Cysteine desulfurase (NFS1) is essential for Fe-S cluster synthesis, and its inhibition sensitizes cancer cells to ferroptosis." (PMID 39737174, 2024). "Normally, cancer cells employ iron via the NFS1 (Cysteine Desulfurase)-ISCU (Iron-Sulfur Cluster Assembly Enzyme)-CISD1/2 (CDGSH Iron-Sulfur Domain Protein 1 and 2) pathway to hinder lipid peroxidation and ferroptosis in mitochondria." (PMID 38292937, 2024).
cancer (continued). "Suppression of NFS1 in murine breast cancer xenografts augments the iron starvation response, increasing intracellular iron stores and sensitizing the cancer to oxidative damage and ferroptosis." (PMID 39188677, 2024). "In fact, work by Alvarez and colleagues demonstrates that various cancer cell lines become dependent on NFS1-mediated generation of iron-sulfur clusters to meet increased metabolic and respiratory demands." (PMID 39188677, 2024). "Cysteine desulfurase (NFS1) is an iron-sulfur cluster biosynthetic enzyme that is essential for cancer cell survival when exposed to oxygen." (PMID 37840106, 2023). "Research on NFS1 has revealed its vital role in regulating iron homeostasis and sensitivity to ferroptosis in cancer cells." (PMID 37345031, 2023). "Other ISC assembly pharmaceutical inhibitors, eprenetapopt or compound #25, reduce ISC biogenesis, restrict cancer cell proliferation, and trigger ferroptosis by inhibiting NFS1 or ISCA2." (PMID 37345031, 2023). "Maintaining a high level of NFS1 gene expression appears essential for survival and growth of cancer cells in high oxygen environment such as cells in a lung tumor or cancer cells during metastasis." (PMID 36282248, 2022). "Suppressing mitochondrial NFS1 (cysteine desulfurase) can sensitize cancer cells to ferroptosis, whereby Fe–S clusters are synthesized using cysteine sulfur." (PMID 36120592, 2022). "Recently, a great deal of work has revolved around the functionality of NFS1, of which its inhibition regulates iron homeostasis and sensitivity to ferroptosis in cancer cells." (PMID 36338346, 2022). "This is verified by the other study reporting that suppression of NFS1, the cysteine desulfurase abstracting the sulfur atom from cysteine for ISC assembly, predisposes cancer cells to ferroptosis and slows tumor growth." (PMID 33801920, 2021). "Because NFS1 can inhibit ferroptosis, targeting NFS1 might enhance treatment efficiency by increasing cancer cell death." (PMID 40822970, 2025). "Importantly, several key ferroptosis drivers and suppressors, including MAPK1, TLR4, ATM, ULK2, NFS1, and HMOX1, have been identified, offering potential therapeutic targets to modulate cancer cell susceptibility to ferroptosis." (PMID 40868287, 2025). "The biological behavior of the tumor likely changes as cancer progresses to a more advanced stage, leading to increased NFS1 expression, which might have a role in tumor migration, resistance, or proliferation." (PMID 40822970, 2025). "Thus, the inhibition of NFS1 activity by Compound 53 resulted in stronger inhibitory effects on A549 cancer cells than on BEAS-2B normal cells." (PMID 40141425, 2025). "Therefore, it is urgent to develop novel, potent inhibitors for studying the biological function of human NFS1 and for treating cancers." (PMID 40141425, 2025). "In line with this, proteins involved in the biosynthesis of iron–sulfur clusters, such as frataxin and cysteine desulfurase NFS1, are upregulated in different types of cancer cells, inducing a reduction in intracellular free iron levels and protecting cells from ferroptosis." (PMID 38539554, 2024). "The findings of this study suggest that NFS1 may be a potential target for developing new cancer therapies via oxaliplatin-triggered PANoptosis." (PMID 38169587, 2024). "To identify the drugs which could have a synergetic effect with ferroptosis-inducers, we screened 75 FDA-approved cancer drugs and found that fludarabine phosphate (F-ara-A) inhibited NFS1 and GSS expression most." (PMID 35067161, 2022). "The existing experimental results indicate that cancer cells rely on the high expression of NFS1." (PMID 34488769, 2021). "Suppression of NFS1 activates canonical iron-starvation responsive proteins regardless of the environmental oxygen level and resulted in the same condition as that of iron overloaded cancer cells undergoing ferroptosis." (PMID 32685019, 2020).
cancer (continued). "Stromal cell infiltration, including cancer-associated fibroblasts (CAFs) and endothelial cells, had a negative correlation trend with NFS1 expression but without adequate statistical support (CAFs [r = −0.237; P = 3.06 × 10−6] and endothelial cells [r = −0.158; P = 2.03 × 10−3])." (PMID 40822970, 2025). "Under oxaliplatin treatment, NFS1 inhibits PANoptosis in a S293 phosphorylation-dependent manner, suggesting that iron-sulfur cluster regulation may be a novel regulatory strategy of PANoptosis in cancer." (PMID 36338346, 2022). "Additionally, FXN could activate NFS1 and accelerate a rate-limiting sulfur transfer step of ISC assembly, and suppression of NFS1 make cancer cell be sensitive to ferroptosis." (PMID 34858857, 2021). "NFS1 deletion in activated CD8+ T cells promotes exhaustion and dampens anti-cancer immunity, while blocking cysteine flux into GSH, or enforcing FeS metabolism, enhance tumor control." (PMID 41659672, 2026). "Upstream sensors like ZBP1, AIM2, and RIPK1, along with regulators identified in cancer-related PANoptosis studies, such as IRF1, ADAR, MAP3K7, and NFS1, were also incorporated for their significant regulatory roles." (PMID 39901195, 2025). "Frataxin (FXN) and NFS1 cysteine desulfurase are both required for ISC synthesis and are overexpressed in cancer cells." (PMID 37190037, 2023). "After multivariate and LASSO analyses, seven cancer-essential FRGs (ISCU, NFS1, MTOR, EIF2S1, HSPA5, AURKA, and RPL8) were used to construct the risk model." (PMID 35756689, 2022). "Compared with normal tissues, the expression of FRGs with higher amplification frequency increased significantly in cancer tissues (e.g., SQLE, NFS1, and ACACA), and vice versa (e.g., GOT1, HMGCR, and FTH1)." (PMID 35444656, 2022). "Multivariate Cox regression showed that seven cancer-essential FRGs (ISCU, NFS1, MTOR, EIF2S1, HSPA5, AURKA, and RPL8) were significantly associated (p<0.05) with OS." (PMID 35756689, 2022). "The identified DEGs related to NFS1 in GO and KEGG gene sets were involved in the pathway related to the cell cycle checkpoint, signaling that included sister chromatid segregation, cancer pathways, focal adhesion, immune responses, and B- and T-cell-mediated immunity." (PMID 40822970, 2025). "Furthermore, the importance of NFS1 and ISC stability in regulation of cancer cell sensitivity to ferroptosis has also been demonstrated." (PMID 36103522, 2022). "For the clinic use, we screened 75 FDA-approved cancer drugs and found that Fludarabine phosphate could decrease the expression of GSS and NFS1 most." (PMID 35067161, 2022). "In summary, our study demonstrates that eprenetapopt targets cancer cells through GSH depletion and inhibiting cysteine desulfurase activity of NFS1, leading to iron-dependent, nonapoptotic ferroptosis." (PMID 36103522, 2022).
tumor (29 papers, 2021 to 2026). "The ESTIMATE algorithm was used to calculate the immune, stromal, and estimated scores of GC patients to further elucidate the association between NFS1 expression and tumor microenvironment (TME)." (PMID 40822970, 2025). "To address whether IscU2-mediated tumor-promoting effect is due to its Fe-S clusters assembly associated function, we generated PaTu-8988t cells depleted of NFS1, a sulfur donor enzyme essential for Fe-S cluster assembly." (PMID 40378953, 2025). "Tumor immune activity was higher in patients with low expression of NFS1 than in patients with high expression of NFS1, according to the association between NFS1 expression and immunologic, estimation, and stromal scores in GC." (PMID 40822970, 2025). "Cysteine desulfurase (NFS1), an iron-sulfur cluster biosynthetic enzyme, decreases ferritin expression and stimulates transferrin expression, thereby increasing the risk of ferroptosis in tumor cells." (PMID 36910646, 2023). "NFS1 encodes several proteins involved in supplying S derived from cysteine to Fe-S clusters and inhibits cysteine transport, triggering ferroptosis and reducing tumor cell growth." (PMID 35756689, 2022). "Upregulation of NFS1 in tumors can enhance tumor cell resistance to ferroptosis; thus, it can promote tumor growth, drug resistance, and metastatic ability." (PMID 41594574, 2025). "The results indicated that NFS1 is negatively correlated with the ESTIMATE, stromal, and immune scores, suggesting that the tumor immune activity of patients with low NFS1 expression was stronger than patients with high NFS1 expression." (PMID 40822970, 2025). "Tumor tissues had substantially greater NFS1 protein levels than peritumoral tissues based on mRNA expression patterns." (PMID 40822970, 2025). "Conversely, the downregulation of NFS1, GCLC, TP63, CD44, and SRC suggests a potential attenuation of antioxidant defense systems, thereby predisposing tumor cells to lipid peroxidation-mediated cell death." (PMID 40868287, 2025). "The TIMER2.0 database was analyzed to provide a deeper understanding of the relationship between the level of NFS1 expression and tumor-infiltrating immune cells, and the tumor purity had a significant positive correlation (r = 0.124; P = 1.55 × 10−2)." (PMID 40822970, 2025). "Previous research has demonstrated that the ISC enzyme, NFS1, functions as a ferroptosis suppressor involved in ferroptosis and tumor growth." (PMID 40822970, 2025). "The current study demonstrated significantly upregulated NFS1 expression in GC tissues compared to non-tumor stomach tissues." (PMID 40822970, 2025). "NFS1 appeared to regulate both immune and stromal cell infiltration within TME, with high NFS1 expression associated with lower immune, stromal, and TME scores, suggesting suppressed immune infiltration and poor tumor prognosis." (PMID 40822970, 2025). "NFS1 helps protect lung tumor cells from ferroptosis by mitigating oxidative damage, thereby promoting tumor survival." (PMID 40841456, 2025). "The level of NFS1 expression was upregulated in GC tissues compared to non-tumor gastric tissues, which was related to clinical characteristics and poor prognosis." (PMID 40822970, 2025). "The results indicated that Adriamycin up-regulated the degree of autophagy and the NFS1 protein levels during tumour treatment, which resulted in MDR." (PMID 38665516, 2024). "According to the analysis of the TCGA data, the expression of MIPEP and NFS1 was higher in tumor tissues in comparison with that in normal tissues; however, the expression of CPT2 and ISCU was lower in tumor tissues in relative to that in normal tissues." (PMID 36776001, 2023). "NFS1 plays a crucial role in suppressing ferroptosis and preventing acidified intracellular pH via the tumor hypoxia-induced pH regulator carbonic anhydrase IX (CAIX), contributing to tumor progression and therapeutic resistance." (PMID 37345031, 2023).
tumor (continued). "In vitro, NFS1 suppression combined with cysteine transport inhibition slows tumor growth by activating ferroptosis." (PMID 37345031, 2023). "Higher levels of both NFS1 and heme suggested that NB-BMSCs used most of the available iron to synthesize iron-compounds to withstand the complex tumor microenvironment." (PMID 36831642, 2023). "Combinatorial genetic depletion of CA9 and NFS1 expression, or pharmacologic inhibition of CAIX/XII in combination with NFS1 depletion, results in increased cellular iron pools, increased lipid peroxidation and increased ferroptosis of tumour cells." (PMID 38099193, 2023). "Consistently, we observed attenuated tumor weights and volumes after silencing NFS1 compared with those in the control group, whereas NFS1 deficiency combined with oxaliplatin treatment also exerted a synergistic effect." (PMID 35221331, 2022). "Knocking down NFS1 sensitizes cells to glutathione biosynthesis inhibition, which increases ROS and induces tumor cell ferroptosis." (PMID 36276162, 2022). "As expected, the combination of NFS1 depletion and oxaliplatin treatment significantly reduced tumor growth and the xenograft tumor weight and achieved the best suppressive effects against tumorigenic activities." (PMID 35221331, 2022). "Consistent with this, our analysis of RNA-Seq data from 159 HBV-related LIHC patients showed that NFS1 mRNA was overexpressed in tumour tissues compared to paired adjacent liver tissues (p ˂ 0.05)." (PMID 34488769, 2021). "First, we evaluated the differential expression of AIFM2 and NFS1 between the tumor tissues and corresponding normal tissues in multiple datasets." (PMID 34778244, 2021). "The results of a meta-analysis after combining 15 independent datasets showed that the expression of AIFM2 in the tumor was lower than that in normal tissues, while opposite results were obtained in NFS1 (p < 0.001)." (PMID 34778244, 2021). "The level of NFS1 expression was inversely correlated with the tumor stage and OS in GC patients." (PMID 40822970, 2025). "Based on functional enrichment analysis, NFS1 may have a role in ferroptosis and the tumor microenvironment (TME), such as epithelial–mesenchymal transition control, and the stromal and immunologic responses." (PMID 40822970, 2025). "In addition, high expression of NFS1, transcriptionally regulated by MYC, was found in tumor tissues and was associated with poor survival and hyposensitivity to chemotherapy in patients with CRC." (PMID 35221331, 2022). "Therefore, tumor cells might develop strategies to inhibit immune function in patients with elevated NFS1 expression." (PMID 40822970, 2025). "Hence, using probe Vis-H2S we could confirm that both autophagy and NFS1 protein are closely related to the MDR of tumour cells." (PMID 38665516, 2024). "Consistently, NFS1 (a sulfur donor enzyme required for Fe–S assembly) depletion was also found able to suppress cell proliferation and increase α-KG levels in PaTu-8988t cells, which highlighted that IscU2-mediated tumor-promoting effect relied on its Fe–S clusters assembly-associated function." (PMID 37488138, 2023). "A hallmark enriched pathway analysis suggested that the expression of NFS1 was positively correlated with the MYC pathway, and NFS1 expression was positively correlated with MYC expression in our CRC tumor tissues and in tissues from the TCGA database." (PMID 35221331, 2022). "By targeting the OPA3–NFS1 axis, suppression of iron death for protecting cardiac toxicity induced by dox and depletion of NFS1 while targeting CAIX enhanced ferroptosis and significantly inhibited tumor growth." (PMID 40822970, 2025). "Furthermore, co-targeting of NFS1 and CAIX activity in vivo results in enhanced tumour growth control compared to targeting each protein individually." (PMID 38099193, 2023). "The genes that regulate iron metabolisms, such as NFS1 (NFS1 cysteine desulfurase) and CISD1 (CDGSH iron–sulfur domain 1), may become novel targets for tumor-targeted therapy." (PMID 34434214, 2021).
tumor (continued). "High NFS1 expression was revealed in multiple tumor tissues and indicated poor survival and poor response to chemotherapy in patients with CRC, which suggested that NFS1 may be a widespread potential prognostic indicator for patients with tumor." (PMID 35221331, 2022). "NFS1 expression was also elevated in lymph-node metastases and recurrent CRC tissues in comparison with paired primary and nonrecurrent tumor tissues, respectively." (PMID 35221331, 2022). "However, there have been no reports on the differential expression of NFS1 and its auxiliary protein LYRM4 in tumour tissues." (PMID 34488769, 2021).